ATM (ATM serine/threonine kinase)
Diseases named in the same sentence as ATM in open-access papers (continued):
Sharing a sentence is not in itself a finding about the gene and the disease.
cancer (continued). "In contrast, ATM loss of function causes ataxia telangiectasia, which occurs at rates of up to ~1:40,000 individuals and is associated with a 20–30% lifetime cancer risk." (PMID 34298632, 2021). "L82 is selectively toxic in BRCA2 or ATM deficient HeLa cells: To evaluate if L82 is also selectively toxic in DSB repair deficient cancer cells, we tested in BRCA2 deficient HeLa and compared to controls." (PMID 34373746, 2021). "More than 72% of mutations of human cancer-associated ATM mutations are missense mutations that are highly enriched in the kinase domain of ATM." (PMID 34771661, 2021). "Biallelic inactivation due to somatic alteration on top of a germline PTV was observed in 4.5% of patients overall, with 81% of these affecting known cancer-predisposition genes (such as ATM)." (PMID 33763108, 2021). "Boadicea v4 Beta (Centre for Cancer Genetic Epidemiology, 2020) considers BRCA1, BRCA2, PALB2, CHEK2, and ATM mutations in the same cancers." (PMID 34406119, 2021). "The mutated form, the Ataxia-telangiectasia mutated (ATM) gene, is involved in cell cycle control, apoptosis, oxidative stress, and telomere maintenance, and its role as a risk factor for cancer development is well established." (PMID 34068084, 2021). "As radiation therapy and many chemotherapy agents attack cancer cells by causing DSBs, elevated ATM’s function and signaling provide tumors with significant advantages to adapt and survive these treatments." (PMID 34070860, 2021). "Inhibiting the function of molecules operative in the DDR, such as ataxia telangiectasia and Rad3-related (ATR), ataxia telangiectasia mutated (ATM), and DNA-dependent protein kinase (DNA-PK), have successfully sensitized cancer cells to ionizing radiation." (PMID 34746010, 2021). "Loss of ATM protein kinase activity results in hypersensitivity to ionizing radiation (IR) and predisposes individuals to cancers." (PMID 34320214, 2021). "POLQ was revealed to be synthetic lethal with DNA repair genes frequently mutated in cancer (such as ATM, ATR, BRCA1/2, FANCD2, Ku70, RAD52, RAD51C, TP53BP1) and extensive efforts for the development of Polθ inhibitors are made by several companies." (PMID 34201502, 2021). "Several association studies have indicated that common variants of ATM are linked to cancer susceptibility, including LC41–43." (PMID 33594163, 2021). "Another study also confirmed that the inhibition of ATM/Chk2 DNA damage checkpoint axis would exhibit anti-cancer efficacy only in ARID1A-mutated cancer cells." (PMID 34715776, 2021). "Several preclinical studies have demonstrated the efficacy of PARP inhibitors in combination with ATR inhibitors in many BRCA-deficient, as well as ATM-deficient, cancer models." (PMID 34027408, 2021). "For this reason, to allow the tumor to grow, in many cancer cells the ATM gene is mutated by missense mutations, especially in the PI3K domain." (PMID 34771661, 2021). "Specific inhibition of both NOX-4 and NOX-2 alleviates increased cancer risk in A-T null mice, whilst the inhibition of ATM increased NOX-4 expression in normal cells." (PMID 33868575, 2021). "In particular, around 0.35% of people carry an ATM mutation, and there is a strong association between mutations in ATM and cancers." (PMID 34068084, 2021). "In response to DNA strand breaks, the activated form of ATM phosphorylates some HR-related factors, such as breast cancer type 1 susceptibility gene (BRCA1) and Fanconi anemia group D2 (FANCD2), triggering the DNA damage repair pathway." (PMID 34135469, 2021). "Recently, a study including patients referred for genetic testing due to personal and/or family histories of cancer found the risk of BC in men harboring an ATM PV to be 1.72 higher (95% CI, 1.08–2.75)." (PMID 34298749, 2021).
cancer (continued). "This would make sense from a cancer cell perspective because the loss of kinase activity would impact a range of processes that ATM/ATR proteins govern, including cellular proliferation; accordingly, such a mutation would confer little selective advantage." (PMID 33742106, 2021). "Despite mutations in genes, such as BRCA and ATM, cancer cells are able to avoid cell death by switching to alternative pathways." (PMID 34712892, 2021). "Among all serine and threonine residues in this IDR, T94 and S98 are in close proximity to the two cancer-associated mutations E95G and S96V, while S111A is a putative ATM/ATR phosphorylation site (SQ)." (PMID 34681076, 2021). "AZD6738 was intensively investigated in various cancers, especially ATM‐deficient cancers as a monotherapy; recent attempt has converged on its combination therapies." (PMID 34977872, 2021). "ATM germline mutations increase cancer susceptibility, and ATM is frequently mutated in a broad range of sporadic cancers." (PMID 35008191, 2021). "Ataxia–Telangiectasia Mutated (ATM) has been implicated in the risk of several cancers, but establishing a causal relationship is often challenging." (PMID 34262154, 2021). "ATM is the primary kinase involved in the cellular response to DNA DSBs, and its loss or inhibition sensitizes cancer cells to chemotherapy." (PMID 34839359, 2021). "Taken together, these evidences underpin a possible role for ATM heterozygous mutations in cancer therapy." (PMID 33407715, 2021). "The ATM R3008H mutation was reported as cancer associated in CLL, MCL, diffuse large B-cell lymphoma (DLBC), and was found as the dominant negative mutation during the analysis of 140 CLL patient peripheral blood mononuclear cells (PBMCs)." (PMID 34771661, 2021). "We find that the conserved ATM/ATR residues mutated in different cancer types show distinct distribution patterns along the respective polypeptides." (PMID 33742106, 2021). "The inclusion of ATM and other genes linked to cancer predisposition syndromes should be considered on the bases of personal or family history of cancer." (PMID 33625671, 2021). "Extensive studies have shown that radioresistance of hypoxic cancer cells is induced by the ataxia-telangiectasia mutated (ATM)-dependent DNA damage repair pathway, particularly through upregulation of homologous recombination activity." (PMID 34135469, 2021). "The purpose of this review is to summarize the information on ATM-kinase dead (KD) mutations coming from A-T or cancer patients and animal models that express an “inactivable” and/or “null” version of ATM." (PMID 34771661, 2021). "Collectively, these results suggest that RNF8 physically binds to and protects ATM-phosphorylated MDC1 from caspase-dependent proteolytic cleavage in BIN1-deficient cancer cells." (PMID 34948122, 2021). "These self-inflicted (“spontaneous”) DNA DSBs (spDSBs) in cancer cells are associated with persistent ATM activation and DDR, and more aggressive tumor types." (PMID 34681703, 2021). "The majority of the ATM/ATR residues implicated in cancer are buried inside the respective enzyme complexes." (PMID 33742106, 2021). "During the past three decades, the study of ATM (ataxia telangiectasia mutated) has played a central role in advancing our understanding of the mammalian DNA damage response, cancer initiation and progression as well as redox signaling pathways." (PMID 34070860, 2021). "We infer that majority of the conserved ATM/ATR residues mutated in cancer are buried within the respective enzyme complexes, irrespective of the cancer type." (PMID 33742106, 2021). "A limitation to the study is that we have only tested synthetic lethality in BRCA2 or ATM deficient HeLa cancer cell line models." (PMID 34373746, 2021).
cancer (continued). "Patients with mutations in ATM gene present with insulin resistance, growth retardation, immune deficiency, and increased susceptibility to cancer." (PMID 34124196, 2021). "A small molecule inhibitor of LIG1 (L82) was tested for synthetic lethality application in XRCC1, BRCA2 or ATM deficient cancer cells." (PMID 34373746, 2021). "ATM germline heterozygous mutations were found in a big screening of 10,389 cases with genetic predisposition in 33 types of cancer, associated with loss of heterozygosity/biallelic two-hit events." (PMID 34771661, 2021). "It has been shown that ATM-dependent stress and dysregulation of inflammatory pathways mediate predisposition to both the metabolic syndrome and cancer." (PMID 34484227, 2021). "Remarkably, two of the four ATR (D1687 and G1691) and two of the four ATM (L2005 and D2016) conserved residues are mutated in cancer." (PMID 33742106, 2021). "Defects in checkpoint signalling components such as ataxia telangiectasia mutated (ATM) occur in a low proportion of cancers and are responsible for reduced DNA repair and increased genomic instability." (PMID 33993200, 2021). "Promising studies demonstrating a positive association of increased residual damage in ATM, Ligase IV deficient radiation sensitive individuals, and in cancer patients experiencing strong acute or late side effects from the radiation treatment are presented." (PMID 33669522, 2021). "In cancer, apigenin has anti-proliferation, cell cycle arrest, and activation of ataxia telangiectasia-mutated (ATM) and H2AX-induced cancer cell apoptosis." (PMID 34356663, 2021). "Reminiscent of the conserved ATM/ATR residues mutated in cancer, majority (12/15) of the Mec1 residues are buried inside the enzyme complex." (PMID 33742106, 2021). "CNV analysis results showed that ATM (22%) was the most frequently mutated gene among cancers and a result similar to that of esFARGs demonstrated a close connection between CNV and mRNA, especially in BRCA." (PMID 34869316, 2021). "All these observations mean that more studies are necessary to establish specific treatments and new gene therapies to defeat ATM-mutated cancer cells." (PMID 34771661, 2021). "One is the PARP1-MYC pathway for BIN1 reduction, which spontaneously emerges when cancer cells become cisplatin-resistant, and the other is the ATM-phosphorylated MDC1-RNF8 signaling pathway by a BIN1 loss." (PMID 34948122, 2021). "Exploiting this concept, ATR inhibitors (ATRi) are in clinical development for the treatment of cancers including those with mutations in the related kinase ataxia telangiectasia mutated (ATM), or high endogenous replication stress." (PMID 34329458, 2021). "This truncating variant was found in the ATM gene, abolishing its kinase activity, and thus probably explaining the strong family history of cancer reported by the patient in question, who carried a classified benign BRCA1 variant." (PMID 34855882, 2021). "Combined treatment with ATRi and PARPi caused 84% cell death of ATM deficient cancer cells in contrast to only 37% growth inhibition in ATM-proficient wild-type cells." (PMID 33352723, 2020). "Based on our data, we propose a model for the allosteric regulation of Rad50 ATP hydrolysis that describes how each of these mutations disrupt ATM signaling in cancer cells." (PMID 31889185, 2020). "Loss of ATM renders cancer cells sensitive to multiple genotoxic therapies, including traditional chemotherapy, as well as the newly developed PARP inhibitors." (PMID 32015826, 2020). "Analysis of ATM mutation frequency in The Cancer Genome Atlas (TCGA) cohort using c-Bioportal indicates that ATM is mutated in approximately 5% of all cancers, with some, such as MCL, with a much higher mutation frequency of ~40%." (PMID 32183301, 2020). "Although genetic variants in ATM have been associated with various cancers, only one genetic variant in ATM, rs227080, was genome-wide significantly associated with LTL in a Singaporean Chinese population." (PMID 32425970, 2020).
cancer (continued). "In vitro and in vivo studies showed that ß-elemenemakes cancer cells prone to radiation by inactivationof the ataxia telangiectasia mutated (ATM) signalingpathway which decreases the repair rate of damagedDNA." (PMID 31376323, 2020). "The mutational status of the ATM gene was obtained through next-generation sequencing using a TruSight Tumor 170 cancer panel." (PMID 32736562, 2020). "Patients with mutations in ATM develop A-T syndrome that are characterised by progressive neurodegeneration, increased risk of cancer development, radiosensitivity and immune system impairment." (PMID 32284789, 2020). "These cancers also had high rates of ATM, POLQ, FANCM mutations, as well as those to several other genes." (PMID 33214570, 2020). "Since ATM inhibition determines uncontrolled cell entry into mitosis by removing several checkpoints control, the use of ATM inhibitors in cancer therapy has been reported to cause sensitization to radiotherapy." (PMID 32932697, 2020). "It was demonstrated that ATM-deficient cancer cells was more sensitive to PARPi than ATM-proficient cells and the combination use of ATM inhibitors enhanced PARPi efficacy." (PMID 32563252, 2020). "For the family with c.8934_8935delTG variant in ATM a first degree cancer affected relative (III.12) turned out to be negative." (PMID 32756499, 2020). "Deleterious mutations and deletions in ATM are common across multiple cancer types, and the presence of ATM alterations in metastatic/advanced UC is a poor prognostic biomarker, irrespective of platinum‐based treatment." (PMID 33098265, 2020). "Preclinical studies demonstrated that ATR inhibition can exploit synthetic lethality (eg, in cancer cells with impaired compensatory DNA damage responses through ATM loss) as monotherapy and combined with DNA-damaging drugs such as carboplatin." (PMID 32568634, 2020). "They showed that treatment of cancer cells with SLs caused accumulation of DNA lesions that triggered activation of ATM and downstream markers of DDR response." (PMID 32218198, 2020). "A-T patients also have an increased susceptibility to malignancy due to genomic instability, and ATM is one of the most frequently mutated genes in many cancers." (PMID 31740029, 2020). "Inactivation of Ataxia-telangiectasia mutated (ATM) gene results in an increased risk to develop cancer." (PMID 33273545, 2020). "Germline alterations in a single copy of a gene critical for radiation damage responses does not necessarily equate to increased risk of radiation-induced toxicity, with the possible exception of the second cancer risk in ATM heterozygous patients." (PMID 33080914, 2020). "Both BRCA2 and ATM play important roles in the DNA repair pathways in human and their mutations increase the risk of cancer development." (PMID 32284789, 2020). "SIRT3 in mitochondria will provide an advantage to ATM deficient cancer cells by stimulating glutamate and glutamine utilization thereby promoting tumor proliferation." (PMID 33273545, 2020). "Variants in CHEK2 and ATM can impact cancer surveillance and cancer screening, as well as prevention for blood relatives." (PMID 32881420, 2020). "ATM heterozygous pathogenic variants have been reported in some cases of familial ovarian, pancreatic, and prostate cancer." (PMID 32733558, 2020).
cancer (continued). "Identifying individuals with a pathogenic germline ATM variant, and therefore, an increased risk of cancer, is critical to early detection efforts that hope to improve patient care by detecting PDAC before it has spread to other sites in the body." (PMID 31963441, 2020). "Heterozygous carriers of pathogenic germline ATM variants have an increased risk of several cancer types, including hematopoietic, breast, pancreatic, and gastric cancer." (PMID 31963441, 2020). "Loss or mutations in ATM have previously been linked, in some cancer models, to greater sensitivity to ATRi monotherapy." (PMID 32741974, 2020). "The BRAF-negative serrated adenoma (AC43) displayed a truncating ATM mutation shared with the matched carcinoma." (PMID 32895052, 2020). "Cancer cells with BRCA1/2 mutation or ataxia telangiectasia mutated (ATM) deficiency cannot repair double-strand DNA breaks and are thus sensitive to PARP inhibition leading to synthetic lethality." (PMID 31632839, 2019). "As yet, there have not been any trials initiated to further elucidate sensitivity of specific cancer subtypes, such as ATM‐deficient tumors, in the clinical setting." (PMID 30714316, 2019). "Since ATM mutations confer a higher risk of developing cancer and radiation toxicity, it is crucial to detect ATM-variants as the underlying cause in any dystonic patient." (PMID 31920950, 2019). "Emerging data from these early-phase studies support the preclinical observations of the synthetic lethality of ATR inhibitors in ATM-deficient cancers." (PMID 31018854, 2019). "Taken into account that the A allele of rs89037 increased the risk of cancer in our meta-analysis, we need to do more efforts to explore its influence on the expression of ATM protein." (PMID 30709340, 2019). "The underlying principles and management frameworks are also applicable to other cancer predisposition genes, particularly the more common, lower penetrance CPGs such as ATM and CHEK2, which will often be incidental findings." (PMID 31360904, 2019). "Taken together, the mutagenicity and drug sensitivity results argue against making a connection between HR-deficient and ATM/CHK2-deficient cancers." (PMID 31727117, 2019). "To evaluate the association between ATM rs189037 and cancer risk based on smoking status, we performed this meta-analysis by a comprehensive literature search via databases of PubMed, Embase, Web of Science and CNKI, updated till January 2019." (PMID 31201228, 2019). "AZD6738 is an analogue of AZ20 that exhibited single-agent anti-tumor activity across cancer cell lines in ATM-deficient." (PMID 30975222, 2019). "Among these genetic causes, ATM sequence variations are a crucial factor for patients regarding cancer susceptibility, disease progression and radiation toxicity." (PMID 31920950, 2019). "Since it has been shown that the loss of ATM also sensitizes cancer cells to DNA-PK inhibitor treatment, we sought to explore the effectiveness of the combination of olaparib and AZD7648 in ATM-deficient models preclinically." (PMID 31699977, 2019). "DNA repair‐targeting therapies, such as ATR and CHK1 inhibitors (which are most effective against cancers carrying ATM mutations), can be used in combination with current genotoxic chemotherapies in CRCs to further improve therapy response." (PMID 30714316, 2019). "In agreement with previous meta-analyses, our work suggested that ATM rs189037 is a risky variant for cancer susceptibility, but we have some new highlights." (PMID 31201228, 2019).